CCR4 (C-C motif chemokine receptor 4)
Diseases named in the same sentence as CCR4 in open-access papers (continued):
Sharing a sentence is not in itself a finding about the gene and the disease.
melanoma (continued). "Using flow cytometry-based cell sorting, we selected for brain metastasizing melanoma cells (HBMMC from the YDFR.CB3 variant), that endogenously express high levels of CCR4." (PMID 28415693, 2017). "The results show that the viability of CCR4hi cells was significantly higher than that of CON cells showing that CCR4 stimulates growth of melanoma cells." (PMID 28415693, 2017). "We also demonstrated that highly malignant vemurafenib (BRAFmt inhibitor)-resistant human melanoma cells expressed high levels of CCR4." (PMID 28415693, 2017). "Although these cell lines were of the same genetic background, primary tumor-derived cells expressed low levels of the chemokine receptor CCR4, whereas brain-metastasizing melanoma cells expressed significantly higher levels of CCR4." (PMID 27598148, 2016). "One can postulate that CCR4 ligands secreted from the brain interact with the CCR4-positive melanoma cells and attract them to the brain." (PMID 23750336, 2013). "Consistent with this and other reports, we have recently identified CCR4 to be highly expressed on the majority of tumor-infiltrating Treg cells in a human melanoma study (manuscript in preparation)." (PMID 23874336, 2013). "In melanoma, CCR4 is essential for guiding Tregs to emerging tumor locations from lymph nodes." (PMID 39143228, 2025). "Furthermore, in malignant melanoma, CCR4 is expressed at higher levels in brain metastasis cells than in the primary cancer cells and is seen as a risk factor for metastasis." (PMID 37371612, 2023). "In another study, we showed that brain microenvironmental cells including astrocytes expressed and released CCL17 and CCL22 two chemokine ligands of the chemokine receptor CCR4, which is expressed by a subpopulation of melanoma cells with brain‐metastasizing capacity." (PMID 32761606, 2021). "Moreover, CCR4 is overexpressed in melanoma tissues from brain metastasis compared with primary melanoma." (PMID 34806028, 2021). "As CCR4 acts as a skin-homing chemokine receptor, tumor-infiltrating Treg cells in skin lesions of melanoma may possess high CCR4 expression." (PMID 34907192, 2021). "Furthermore, numerous reports have highlighted the role of CCR4 in the recruitment of Tregs in human tumors, such as breast, ovarian, colon, gastric, lung, brain and prostate carcinoma, as well as in melanoma and HL and diffuse large B-cell lymphoma." (PMID 33924428, 2021). "Their results demonstrated that CCL17 (but not CCL22) was sufficient to enhance melanoma cell invasiveness in the brain, and blocking CCR4 in vivo using a CCR4-antagonist small molecule reduced the tumorigenicity and micrometastasis formation of melanoma cells." (PMID 33466236, 2021). "Interestingly, very recently, it has been reported in an inducible autochthonous model of melanoma that the expression of the oncogenic BRAFV600E mutation in melanocytes resulted in nevus formation, CCR4 induction, and Treg cell recruitment." (PMID 31028434, 2019). "Collectively these results suggest that CCR4 overexpression on melanoma tumors might enhance their potential to metastasize to the brain." (PMID 30420855, 2018). "Furthermore, CCR4 is more highly expressed on melanoma brain metastases than on paired-primary melanoma tumors." (PMID 30420855, 2018). "Taken together, these findings implicate CCR4 as a driver of melanoma brain metastasis." (PMID 28415693, 2017). "Microglial cells interacted with melanoma cells and altered the expression of CCR4 in these cells." (PMID 28415693, 2017). "The next set of experiments was aimed to establish whether CCR4 is expressed by brain-metastasizing melanoma cells in-vivo." (PMID 28415693, 2017). "We suggest that the up-regulated levels of CCL17 in the brain could chemo-attract CCR4-expressing melanoma cells towards this organ." (PMID 28415693, 2017). "Moreover, we found that the expression of CCR4 is significantly higher in paired clinical specimens of melanoma metastases than in samples of primary tumors from the same patients." (PMID 28415693, 2017).
melanoma (continued). "Based on the results of the present study we suggest that CCR4 could serve as a target for the therapy of melanoma." (PMID 28415693, 2017). "The present study shows that indeed CCR4 is a determinant of melanoma brain metastasis." (PMID 28415693, 2017). "Based on these results we evaluated the effect of the CCR4 antagonist on the migration of brain-metastasizing melanoma cells, expressing high levels of CCR4, towards astrocyte secreted factors as compared with the migration of local cutaneous melanoma cells, expressing very low levels of CCR4." (PMID 28415693, 2017). "Transwell migration assays using recombinant CCL17 or CCL22 revealed that CCL17, but not CCL22 (data not shown), significantly facilitated migration of the CCR4hi cells compared to control cells (CON), indicating that expression of CCR4 facilitates melanoma cell migration." (PMID 28415693, 2017). "Moreover, soluble factors from the brain microenvironment upregulated CCR4 expression on melanoma cells." (PMID 28415693, 2017). "This should be a feasible approach as we have recently tested the effect of anti-CCR4 antibody on subsets of human Treg cells in melanoma patients and found it to efficiently eliminate a population of CCR4-expressing effector Tregs while sparing naïve Treg populations (manuscript in preparation)." (PMID 23874336, 2013). "In a melanoma study, CCR4 was required for the homing Tregs to nascent tumor sites from LNs, and BRAFV600E signaling controlled the expression of CCR4 chemokines, raising the possibility that inhibiting this signaling with BRAF inhibitors may have reduced Treg recruitment to the tumor." (PMID 34417572, 2022). "Hence, with the intention of blocking the interaction of cancer cells expressing CCR2 (and CCR4) with MCP-1 secreted in MBM (from astrocytes and other sources of cells in the brain, including tumor cells), we knocked out CCR2 and CCR4 genes in melanoma cells, using the CRISPR/Cas9 system." (PMID 35980743, 2022). "For example, the anti-CCR4 monoclonal antibody mogamulizumab is already clinically approved to treat haematological malignancies and may also be applied to the treatment of melanoma." (PMID 34830780, 2021). "Taken together the results of these experiments indicated that targeting CCR4 expressed on melanoma cells ameliorates their malignant phenotype in-vitro and in-vivo suggesting that CCR4 antagonists may have a therapeutic potential in melanoma." (PMID 28415693, 2017). "Thus, the interaction of CCR4, expressed by melanoma cells, with its CCL17 ligand in the brain may contributes to targeted migration of melanoma cells to the brain." (PMID 28415693, 2017). "The mutually exclusive pattern of mutations in this CCR4-NOT complex in 20% of melanoma patients illustrates that all members of the complex could play an important role in tumor biology." (PMID 25544760, 2015). "Mutually exclusive mutations of other members of the CCR4-NOT complex were found in ~20% of the TCGA melanoma dataset suggesting the complex may play an important role in melanoma biology." (PMID 25544760, 2015). "Compared to primary melanomas, MCP‐1, and its corresponding receptors CCR2 and CCR4, have been shown to be overexpressed in MBM." (PMID 37759347, 2023). "Naama Margolis and colleagues found that ADAR1 regulates the production of chemokines in melanoma, such as CCR4, CCR5, and CXCR3, in melanoma to recruit T lymphocytes." (PMID 37217462, 2023). "The major chemokine/chemokine receptor interactions occurring in melanoma development and progression include the CXCR4/CXCR7/CXCL12, CXCR3/CXCL9,10,11, CXCR1,2/CXCL8, CCR2/CCL2, CCR4/CCL17,22, CCR5/CCL5, CCR7/CCL21 and CCR10/CCL27 axes." (PMID 37170733, 2023). "In murine breast and melanoma tumor models, genetic ablation of FOXP3 reduced CCR4+ Treg infiltration and tumor size while also restoring anti-tumor immunity." (PMID 35222362, 2022).
melanoma (continued). "CCL1 and CCL22, the main ligands for CCR8 and CCR4, respectively, have been shown to be upregulated both at the gene and protein levels in the TME of melanoma, suggesting that melanoma cells are able to actively recruit T-regs." (PMID 34830780, 2021). "CCL2 induces overexpression of the Cavα2δ1 subunit in the VGCCs of primary afferents and melanoma cells, as well as overexpression of CCL2 receptors (CCR2 and CCR4)." (PMID 34575835, 2021). "We also observed that the expression of CXCR3, CCR4 and CCR5 was significantly higher on T cells and NK cells in peripheral blood of melanoma patients than in healthy controls." (PMID 32002296, 2020). "In a recent comprehensive study, melanoma cells were shown to express a whole set of chemokine receptors, including CCR3, CCR4, CXCR3, CXCR7, CX3CR1 and membrane CX3CL1." (PMID 23344048, 2013). "To overcome the lack of therapeutic efficacy by either blocking MCP-1 or blocking CCR2 or CCR4 with pharmacological agents, we present a CRISPR/Cas9 double K/O in melanoma cells to target the activation of an alternative compensatory pathway activated by MCP-1 involved in MBM, such as MCP-1/CCR4." (PMID 35980743, 2022). "Furthermore, melphalan-exposed melanoma cells triggered upregulation of CXCR3, CCR4, CCR5 and PD-1 on co-cultured T cells and/or NK cells." (PMID 32002296, 2020). "The CCR4 antagonist significantly inhibited astrocyte-induced migration of brain-metastasizing melanoma cells but did not affect the migration of local melanoma cell, further supporting a role for CCR4 in facilitating brain metastasis." (PMID 28415693, 2017). "Subsequent studies have shown increased infiltration and anti-tumor responses of adoptively transferred mouse and human T cells engineered to express, for instance, CCR4, CXCR2 and CCR2 in transplantable mouse models of Hodgkin’s lymphoma, melanoma and mesothelioma, respectively." (PMID 28923105, 2017). "The same group has reported that brain-derived soluble factors upregulate the expression of CCR4 in both cutaneous and brain-metastasizing melanoma cells and enhance the migration of the latter, but not that of the cutaneous variants." (PMID 23750336, 2013). "In addition, the inflammatory response pathway was found to be enriched in MES samples as compared to MEL, accompanied by significantly high expression of CXCL1 and its receptor, CXCR2, as well as chemokine receptors CCR4 and CCR6, in melanomas characterised by the invasive gene signature." (PMID 36765773, 2023). "This subpopulation is more highly tumorigenic than melanoma cells lacking CCR4." (PMID 32761606, 2021). "We found that B16–BL6/Zs green melanoma cells secrete CCL2 spontaneously; thus, the tumor mass could directly affect the excitability of nociceptive neurons in our animals, and might induce the upregulation of CCL2 receptors (CCR2 and CCR4), as has been previously suggested." (PMID 34575835, 2021). "Moreover, in stage IV melanoma patients with brain metastases, CCL18, CCR1, CCR4, CD274, CSF2, EGF, and PTGS2 genes were significantly over-expressed (p < 0.001, versus patients without melanoma brain metastasis)." (PMID 37091783, 2023).
asthma (46 papers, 2004 to 2025). "CCR4 has been associated with asthma, and CCR4-deficient mice display reduced airway hyperresponsiveness following chronic lung allergen challenge." (PMID 31024538, 2019). "In asthma, CCR4 expression is associated with lung trafficking potential of pathogenic memory Th2 cell and can be found on most lung-homing tissue-resident memory T cells." (PMID 31222115, 2019). "Reduction of the CCR4 ligand, CCL17 by H4R antagonist in a comparable study also suggests a direct inhibition of CCR4 + Th2 cells, a sub-population implicated in asthma pathogenesis." (PMID 20573261, 2010). "Furthermore, both chemokines signal through CCR4, and both have been implicated in type 2 immune responses and were shown to play a role in asthma and in atopic dermatitis." (PMID 33808372, 2021). "Specifically, Th2-type CD4+ T-cells, which are involved in allergic inflammatory disorders such as asthma, atopic dermatitis, and allergic rhinitis, express CCR4." (PMID 38804300, 2024). "Recent studies provide new evidence that CC chemokine receptor 4 (CCR4) is important in the pathogenesis of many diseases, such as diabetes, multiple sclerosis, asthma, dermatitis, and cancer." (PMID 36555280, 2022). "The contribution of CCR4 to the pathogenesis of autoimmune encephalitis, multiple sclerosis, asthma, and atopic dermatitis has been shown." (PMID 36555280, 2022). "Intriguingly, in our study, ZKPC was found to be able to resist the supernatant of M2-induced decrease in cell viability and apoptosis, and reduce the levels of chemokine receptors, CCR3, and CCR4, which are involved in lung inflammation in asthma." (PMID 34608825, 2021). "CCL17 and its receptor CCR4 play a central role in the pathogenesis of endotoxin shock and inflammatory diseases such as atopic dermatitis and asthma." (PMID 33648537, 2021). "Children with a diagnosis of asthma had an increased percentage of type 2 T cells identified as CD4+CCR4+, which demonstrated increased activation of STAT5 following stimulation with 100 U/ml IL-2 for 10 min." (PMID 32985505, 2020). "We also found that the differences of sialyl LeX positive and sialyl 6-sulfo LeX positive cells among memory Th cells in childhood asthma exist predominantly in CCR4+CCR7− effector memory Th subset, instead of in CCR7+ central memory Th subset." (PMID 31222115, 2019). "The chemokines CCL3, CCL4, and CCL5 are all associated with the migration of macrophages and other leukocytes through their binding to CCR1, CCR4, and CCR5, and have been linked with asthma." (PMID 31024538, 2019). "Previous studies have shown that the proportion of CCR4+ memory Th cells expressing sialyl 6-sulfo Lewis X (LeX) is elevated in asthma patients." (PMID 31222115, 2019). "This is supported by findings in the allergy and asthma research fields that demonstrate the involvement of CCR4 and other chemokine receptors in recruiting Th2-like cells to the lung." (PMID 31396211, 2019). "On the contrary, the proportion of sialyl LeX positive FOXP3+CCR7+CCR4− Treg cells among CD4+ T cells was lower in moderate-to-severe asthma compared with healthy controls (post hoc p < 0.05)." (PMID 31222115, 2019). "CCR2 receptor blockade prevented asthma in a primate model, and anti-CCR3 and anti-CCR4 were tested in asthma." (PMID 29670611, 2018). "The roles of CCR4+ T cells in the pathogenesis of asthma are still controversial in both a murine model of asthma and asthma patients." (PMID 29507584, 2018). "A previous study reported that corticosteroid treatment slightly decreased the percentage of CCR4+ total T cells, but it was performed with patients that had mild and stable asthma." (PMID 29507584, 2018). "More recently, a study by Vijayanand and colleagues demonstrated increased CCR4 expression on T cells isolated from patients with asthma." (PMID 25981299, 2015). "A considerable body of evidence points to a role for CCR4 and its ligands in allergic diseases, notably asthma." (PMID 25981299, 2015).
asthma (continued). "This chemokine is elevated in sera of asthma patients and is responsible for establishing inflammatory sites through CCR4-mediated recruitment of immune cells." (PMID 24339934, 2013). "A role for CCL17 in fungus-induced asthma has been previously established using either CCR4 KO mice or treatment with polyclonal CCL17-specific antibodies." (PMID 24339934, 2013). "The CC-chemokine receptor 4 (CCR4) is thought potentially to play a critical role in asthma pathogenesis due to its ability to recruit type 2 T-helper lymphocytes to the inflamed airways." (PMID 23448278, 2013). "In murine asthmatic models, the CCR4 blocking antibody attenuates airway eosinophilia and goblet cell hyperplasia and diminishes IgE synthesis and bronchial hyperreactivity." (PMID 22907157, 2012). "CC chemokine receptor 4 (CCR4) is a pivotal factor in the development of allergic inflammations, such as asthma, dermatitis, and rhinitis." (PMID 22907157, 2012). "In the study, administration of a CCR4-blocking antibody abolished airway eosinophilia, goblet cell hyperplasia, IgE synthesis and bronchial hyperreactivity." (PMID 22125604, 2011). "The effectiveness of anti-CCL17 and anti-CCL22 antibodies in murine asthma models supports and strengthens a prevalent function for CCR4 on Th2 cells; as Th1 and Th2 responses have opposing functions, CCR4 antagonists act as adjuvants to steer the immune response toward a Th1-type response." (PMID 38804300, 2024). "In human asthma, CCR4+ Th2 cells are increased and correlate with asthma severity." (PMID 35479312, 2022). "Indeed, based on its predominant expression in Th2 lymphocytes, CCR4 has long been considered as candidate target for drug development against allergy and asthma." (PMID 33669094, 2021). "Improved characterization of the roles of the memory Th cells and Treg cells in asthma, especially their CCR7+ and CCR4+ subsets, could improve our understanding of asthma immunology." (PMID 31222115, 2019). "Accordingly, the frequency of CCR4+CCR7+ memory CD4+ T cells correlated with asthma severity." (PMID 29507584, 2018). "We next investigated whether the increase of circulating CCR4+ CD4+ T cells in patients could be a feature of asthma subtypes." (PMID 29507584, 2018). "The increase of CCR4+ CD4+ T cells in asthma patients has been previously reported." (PMID 29507584, 2018). "In addition, the percentage of circulating CCR4+CD45RA−CD45RO+CCR7+ CD4+ T cells in patients correlated with asthma severity, as measured with % predicted FEV1 scores." (PMID 29507584, 2018). "The inverse correlation between the frequency of CCR4+ CD4+ Tcm cells and asthma severity further support that CCR4+ CD4+ Tcm cells could play an important role in the pathogenesis of atopic asthma." (PMID 29507584, 2018). "An obvious potential caveat of total CCR4 blockade as an asthma treatment is the potential for the impairment of regulatory T cell recruitment, since T-regulatory cells (Tregs) have been shown to express CCR4 and to migrate in vitro in response to both CCL17 and CCL22." (PMID 25981299, 2015). "In mice, CCL17 has been linked with various inflammatory conditions presumably by setting the stage for a Th2 response through recruitment of CCR4+ immune cells, from controlling schistosomiasis and colitis to conditions of chronic pulmonary inflammation seen in fibrosis and asthma models." (PMID 24339934, 2013). "In particular, CCR4 is expressed on Th2-type CD4+ T cells which have been linked to allergic inflammatory diseases such as asthma, atopic dermatitis and allergic rhinitis, but is not expressed by Th1 T cells that typically are involved in cell-mediated protection against infection." (PMID 20011659, 2009). "However many CCR4 antagonists are now in preclinical development and have been shown to be effective in reducing the chemotaxis of Th2 cells in vitro and lung eosinophilic inflammation in an animal model of asthma." (PMID 18315837, 2008).